PCDHB16 (protocadherin beta 16)
Description:
Potential calcium-dependent cell-adhesion protein. May be involved in the establishment and maintenance of specific neuronal connections in the brain.
Synonyms: KIAA1621; PCDH3X; PCDHB8a; PCDH-BETA16; ME1
Tractability: Antibody: UniProt predicts a signal peptide or a membrane-spanning region; its Gene Ontology location is reachable by antibodies, with medium confidence; the Human Protein Atlas places it where antibodies can reach. PROTAC: its protein half-life has been measured.
Gene: Protein-coding gene on chromosome 5 (141,182,387 to 141,186,226, forward strand). Ensembl gene ENSG00000272674.
Subcellular location: Membrane
Subcellular location (Human Protein Atlas): Plasma membrane; Vesicles
Gene Ontology:
Molecular function: cell adhesion molecule binding; calcium ion binding
Biological process: calcium-dependent cell-cell adhesion; cell adhesion; chemical synaptic transmission; synapse assembly; homophilic cell-cell adhesion; nervous system development
Cellular component: membrane; plasma membrane; synapse
Genetic constraint (gnomAD): Missense variants: 1,026 observed, 952.56 expected, observed/expected ratio (o/e) 1.08, 90% interval 1.02 to 1.13. Synonymous variants: 444 observed, 412.54 expected, observed/expected ratio (o/e) 1.08, 90% interval 1 to 1.16.
Homologues: Orthologues: chimpanzee PCDHB16 (98% identical), mouse Pcdhb17 (76% identical), rabbit PCDHB16 (71% identical), dog PCDHB16 (71% identical). Paralogues in human: PCDHB8 (79% identical), PCDHB13 (79% identical), PCDHB3 (78% identical), PCDHB2 (77% identical), PCDHB15 (77% identical), PCDHB14 (77% identical), PCDHB5 (77% identical), PCDHB6 (77% identical), PCDHB11 (76% identical), PCDHB12 (76% identical), PCDHB4 (75% identical), PCDHB7 (74% identical), and 49 more.
Diseases named in the same sentence as PCDHB16 in open-access papers:
PCDHB16 is named in the same sentence as 8 diseases in open-access papers, as found by Europe PMC text mining. Sharing a sentence is not in itself a finding about the gene and the disease. The quoted sentences say what the papers report.
diabetes (1 paper, 2022). "There were 8 differentially methylated genes (CDH2/PCDHB10/PCDHB11/PCDHB14/PCDHB16/PCDHB3/PCDHB6/PCDHB9) in the LAA subgroup and 1 (CDH2) in the SVD subgroup after adjusting for smoking, drinking, history of hypertension and diabetes, and blood lipid levels (p < 0.05)." (PMID 35480311, 2022).
neuroblastoma (1 paper, 2022). Neuroblastoma (NB) is the most common solid, extracranial childhood tumor. "On chromosome 5, two genes were chosen from the PCDHB hypermethylation cluster: PCDHB15 and PCDHB16 that are CIMP-associated with bad prognosis in neuroblastoma." (PMID 36125262, 2022).
schizophrenia (1 paper, 2018). A major psychotic disorder characterized by abnormalities in the perception or expression of reality. "However, no study to date have been performed regarding the protocadherin beta 16 (Pcdhb16) as a schizophrenia-associated gene." (PMID 29962931, 2018).
cancer (2 papers, 2015 to 2020). A tumor composed of atypical neoplastic, often pleomorphic cells that invade other tissues. "CUVs from the genes MYO1E, SARDH and ISLR appeared in two distinct individuals with cancer from this non-Caucasian cohort, while CUVs from PCDHB16 and known CPG BMPR1A appeared in a single individual with cancer." (PMID 32778766, 2020).
tumour (1 paper, 2022). "Four genes (MYH1, PCDHB16, PCDHB15, and BCL2L10) showed a differential methylation profile between metastatic and primary tumour tissue samples (data not shown)." (PMID 36125262, 2022).
PCDHB16 also shares sentences with these, for which no sentence is quoted: Cirrhosis (1 paper); hearing loss (1); Hypertension (1).